DEK (DEK proto-oncogene)
Description:
Involved in chromatin organization.
Synonyms: D6S231E
Tractability: PROTAC: ubiquitination databases record sites on it; its protein half-life has been measured.
Gene: Protein-coding gene on chromosome 6 (18,223,860 to 18,265,997, reverse strand). Ensembl gene ENSG00000124795.
Subcellular location: Nucleus
Subcellular location (Human Protein Atlas): Nucleoplasm; Cytosol
Pathways (Reactome):
Gene expression (Transcription): B-WICH complex positively regulates rRNA expression; Transcriptional regulation by the AP-2 (TFAP2) family of transcription factors
Developmental Biology: Transcriptional regulation of granulopoiesis
Gene Ontology:
Molecular function: histone binding; protein binding; RNA binding; DNA binding
Biological process: positive regulation of transcription by RNA polymerase III; regulation of double-strand break repair; chromatin remodeling; positive regulation of transcription by RNA polymerase I; positive regulation of transcription by RNA polymerase II; regulation of transcription by RNA polymerase II; signal transduction; transcription by RNA polymerase II; viral genome replication; chromatin organization
Cellular component: B-WICH complex; nucleoplasm; nucleus; nucleolus; contractile muscle fiber
Genetic constraint (gnomAD): Loss-of-function variants: 19 observed, 36.3 expected, observed/expected ratio (o/e) 0.52, 90% interval 0.36 to 0.77. The upper end of that interval is the gene's LOEUF score, 0.77, which puts it in group 3 of 6, group 1 being the genes least tolerant of losing a copy. Missense variants: 365 observed, 387.88 expected, observed/expected ratio (o/e) 0.94, 90% interval 0.86 to 1.03. Synonymous variants: 150 observed, 136.11 expected, observed/expected ratio (o/e) 1.1, 90% interval 0.96 to 1.26.
Homologues: Orthologues: chimpanzee DEK (99% identical), macaque DEK (99% identical), guinea pig DEK (94% identical), dog DEK (94% identical), rabbit DEK (94% identical), rat Dek (92% identical), mouse Dek (91% identical), tropical clawed frog dek (61% identical), zebrafish dek (43% identical), Drosophila melanogaster Dek (40% identical).
Diseases named in the same sentence as DEK in open-access papers:
DEK is named in the same sentence as 105 diseases in open-access papers, as found by Europe PMC text mining. Sharing a sentence is not in itself a finding about the gene and the disease. The quoted sentences say what the papers report.
breast carcinoma (28 papers, 2013 to 2025). "In the present study, 1H-NMR spectroscopy was employed as an exploratory tool to identify dysregulated lipid families and characterize the lipid metabolic profile of murine breast cancer cells with respect to loss of RON or DEK expression." (PMID 39351361, 2024). "DEK is a chromatin-associated oncogene that also promotes breast cancer stemness and metastasis and can be stimulated by RON signaling." (PMID 39351361, 2024). "DEK is highly expressed in breast cancer and is associated with malignant phenotype and progression." (PMID 35742899, 2022). "DEK has been proven to promote the formation and development of solid tumors: for instance, DEK is highly expressed in breast cancer and is associated with a malignant phenotype and progression." (PMID 35698073, 2022). "High expression of DEK associates with poor prognosis of various cancers, such as breast cancer and prostate cancer." (PMID 26988756, 2016). "We hypothesized that RON and DEK upregulation in breast cancer is required for lipid metabolism that is linked to poor outcomes." (PMID 39351361, 2024). "DEK regulate EMT associated with breast cancer metastasis via PI3K/AKT/mTOR pathway in TNBC cells." (PMID 32257110, 2020). "DEK has been implicated in various kinds of cancer including breast cancer metastasis." (PMID 32257110, 2020). "RON and DEK are implicated in breast cancer metastasis and recurrence, and since these same phenotypes have been linked to lipid dysregulation, the gene signature discovered here might have diagnostic and prognostic potential for patients with breast and other cancer types." (PMID 39351361, 2024). "We, and others, have reported that DEK mRNA and protein are over-expressed in many human solid cancers, including 62–92% of breast cancers." (PMID 40562540, 2025). "We found that breast cancer cells with RON and DEK loss of function harbor independent dysregulation of defined lipid metabolites, including cholesterol, unsaturated fatty acids, glycerol, sphingomyelin, and glycerophospholipids." (PMID 39351361, 2024). "The literature combined with the lipid data presented in this report supports possible roles for RON and DEK in the reprogramming of breast cancer cells toward a cancer stem cell phenotype." (PMID 39351361, 2024). "Here, we applied the ICCS approach and PLA analysis to investigate the spatial correlation between the nuclear distribution of DEK protein and the chromatin pattern in the context of breast cancer progression." (PMID 37550322, 2023). "Together, these results emphasize the molecular connection between DEK protein and the regulation of active sites of chromatin in the breast cancer model." (PMID 37550322, 2023). "This investigation into the nanoscale arrangement of the DEK protein in breast cancer cell lines and its response to chromatin decompaction induced by Trichostatin A (TSA) treatment can be enhanced in several ways." (PMID 38026229, 2023). "In this work, we investigated the nanoscale characteristics of such clusters in normal-like and aggressive types of breast cancer cell lines to study if DEK’s overexpression correlates with its cluster features." (PMID 38026229, 2023). "Yang indicated that DEK promote the proliferation and invasion of breast cancer cells by activating the Wnt signaling pathway." (PMID 35698073, 2022). "Mechanistically, RON and DEK promote β-catenin activation through independent mechanisms that synergize to support breast cancer stem cell self-renewal and breast cancer metastasis in preclinical models." (PMID 36067206, 2022).
breast carcinoma (continued). "Both RON and DEK have been shown to augment breast cancer stem cells, a subpopulation of treatment evading, tumor-initiating cells implicated in cancer recurrence." (PMID 36067206, 2022). "This study examined gene-metabolite relationships by focusing on the RON/DEK/ signaling axis, which is a known driver of breast cancer metastasis and recurrence." (PMID 36067206, 2022). "DEK is known as an oncogene and is overexpressed in multiple cancers, such as melanoma, gastric cancer, and breast cancer." (PMID 34065619, 2021). "A positive correlation with angiogenesis factor VEGF and formation of micro-vessel among a cohort of 58 breast cancer patients further validated the role of DEK in breast cancer." (PMID 32257110, 2020). "It has been found that approximately 80% of ovarian cancers have DPH1 gene deletions and that ELP3 is up-regulated in breast cancer cells, which in turn leads to increased levels of the oncoprotein DEK." (PMID 28555368, 2017). "The conditioned medium from DEK knockdown breast cancer cells repressed HUVEC tube formation, a capillary-like structure with a lumen." (PMID 26988756, 2016). "To investigate the mechanism by which DEK enhances VEGF transcription in breast cancer cells, we first determined DEK binding sites on the VEGF promoter using luciferase reporter assay." (PMID 26988756, 2016). "CAM treated with the conditioned medium from DEK knockdown breast cancer cells had reduced number of new blood vessels and re-expression of DEK in DEK knockdown cells rescued this effect." (PMID 26988756, 2016). "In murine breast tumor models, DEK also drives expression of Wnt ligands, resulting in the promotion of β-catenin transcriptional activity, which has also been noted in human breast cancer cells." (PMID 26425120, 2015). "In breast cancer cell lines, DEK overexpression promotes cell growth and mobility by inducing β-catenin nuclear translocation and enhances tumor growth and metastasis by activating Wnt/β-catenin autocrine and paracrine signaling loops." (PMID 26425120, 2015). "High expression levels of the human DEK gene have been correlated with numerous human malignancies such as glioblastoma, melanoma, breast cancer, ovarian cancer and hepatocellular carcinoma." (PMID 23902796, 2013). "Not only does the proto‐oncogene DEK induce an immunodeficient tumor environment with M2, but it has also been connected to poorer clinicopathological features and a worse prognosis for individuals with breast cancer." (PMID 40384436, 2025). "Indeed, DEK as a mediator of exit from quiescence was previously reported in breast cancer stem cells, hematopoietic multipotent progentitors, muscle satellite (progenitor) cells and Artemia crustaceans." (PMID 40562540, 2025). "Taken together, RON and DEK differentially regulate lipid metabolism in a manner that predicts and may promote breast cancer metastasis and recurrence." (PMID 39351361, 2024). "Considering the overexpression of DEK in breast cancer samples, we speculated that its nanoscale organization would differ if compared with normal-like cells." (PMID 38026229, 2023). "Thus, this study suggests that the role of DEK on transcriptionally active chromatin regions varies depending on the subtype of the breast cancer cell line." (PMID 37550322, 2023). "The overexpression of DEK is found in a majority of solid tumors, including retinoblastoma, adenocarcinoma, lung cancer, bladder cancer, prostate cancer, cervical cancer, melanoma, breast cancer, and esophageal and oral squamous cell carcinoma." (PMID 36275000, 2022). "Recently, it was determined that increased DEK expression in breast cancer cells results in differential expression of multiple cytokines that contribute to M2 polarization of tumor-associated macrophages, potentially creating an immune suppressed tumor microenvironment." (PMID 36275000, 2022).
breast carcinoma (continued). "Among the candidates unique to our study are several proteins described to be involved in different cancer types in humans: for example, NOLC1 in multidrug resistant non-small cell lung cancer (the same cancer MALAT1 has originally been identified), DEK in breast cancer and SUB1 in prostate cancer." (PMID 32050583, 2020). "Additionally, DEK regulate tumor angiogenesis in breast cancer by binding to the DEK Response Element (DRE) in the VEGF promoter thereby inducing HIF-α and acetyltransferase P300 recruitment within the promoter." (PMID 32257110, 2020). "Partner enzymes in U34 tRNA modification, including ELP3 and CTU1/2 were found to be up-regulated in human breast cancers and sustain metastasis, through the translation of the oncoprotein DEK, that promotes the translation of the pro-invasive transcription factor LEF1." (PMID 31238876, 2019). "This suggests DEK may regulate cancer stem cell metabolism which is in line with data from a breast cancer study showing DEK is required to sustain the growth of a stem cell population." (PMID 28558019, 2017). "DEK has been shown to promote breast cancer cell invasion by inducing β-catenin activity." (PMID 27057626, 2016). "DEK is overexpressed in multiple cancers, including breast cancer and prostate cancer." (PMID 26988756, 2016). "Our previous study showed that DEK protein expression was closely related with the proliferation of both ovarian and breast cancers, and that its over expression was significantly correlated with the increased Ki-67 proliferation index in uterine cervical cancers." (PMID 23902796, 2013). "This suggests that RON and DEK may control pathways that influence the physical properties of membranes including fluidity and signaling, important possible contributors to metastasis and recurrence in breast cancer." (PMID 39351361, 2024). "Thus, both production and utilization of creatine energy storage may be regulated by the RON/DEK/β-catenin axis in breast cancer." (PMID 36067206, 2022). "It is also plausible that WSB-1 could regulate the expression of only a selected number of HIF target genes, rather than all HIF-dependent expression, as it is the case in breast cancer, respectively, for co-factors p300 and DEK for GLUT-1 (SLC2A1) and VEGF (VEGFA) expression." (PMID 29540773, 2018). "DEK and EZH2 protein and mRNA expression levels were, indeed, strongly positively correlated in human breast cancers." (PMID 40562540, 2025). "To determine if DEK and EZH2 expression correlate in other models, we quantified their expression in breast cancer datasets." (PMID 40562540, 2025). "We posit that metabolic reprogramming regulated by RON/DEK/β-catenin may be similarly controlled by other oncogenic drivers of metastasis/recurrence and may therefore more broadly define key metabolic drivers of breast cancer stages responsible for the majority of cancer-related deaths." (PMID 36067206, 2022). "The results revealed that β-lap down-regulated Skp2 and DEK expression in MCF-7 and MDA-MB-231 breast cancer cell lines." (PMID 28578385, 2017). "Recent study had shown that DEK as a novel coactivator for HIF-1a in regulation of VEGF transcription and a promoter of angiogenesis in breast cancer." (PMID 29228721, 2017). "We further confirmed DEK overexpression-mediated enhancement of VEGF-Luc reporter activity using our DEK expression construct in ZR75-1, MCF-7 and MDA-MB-231 breast cancer cells." (PMID 26988756, 2016). "This implies that RON, but not DEK, potentially promotes sphingomyelin synthesis and breast cancer progression." (PMID 39351361, 2024). "R7 and MRBC are murine breast cancer cells that express RON, DEK, and β-catenin." (PMID 36067206, 2022). "Importantly, expression of DEK positively correlated with VEGF expression and microvessel number in 58 human breast cancer tissues (P = 0.001 and P = 3.602 × 10−6, respectively)." (PMID 26988756, 2016).
breast carcinoma (continued). "Since DEK promotes VEGF secretion in breast cancer cells in HIF-1α-dependent and -independent manners, we tested the effect of the conditioned medium derived from knockdown DEK or DEK and HIF-1α knockdown stable breast cancer cell lines on HUVEC proliferation and migration." (PMID 26988756, 2016). "Moreover, DEK expression positively correlates with the expression of VEGF and microvessel number in breast cancer patients, indicating the clinical relevance." (PMID 26988756, 2016). "Consistent with previous reports, DEK was overexpressed in breast cancer patients (data not shown)." (PMID 26988756, 2016). "Our previous data also showed that DEK protein was strongly positive in breast cancers and DCIS (ductal carcinoma in situ), but negative in normal breast glands, demonstrating that DEK protein expression levels might be used as a biomarker for early diagnosis of breast cancers." (PMID 23902796, 2013). "Moreover, we identified candidate metabolic enzyme targets and hypothesized that the expression of underlying genes that encode these targets can form a gene signature with predictive capacity for breast cancer patient outcomes irrespective of RON/DEK/β-catenin status." (PMID 36067206, 2022). "Interestingly, DEK and EZH2 mRNA levels tended to be higher in estrogen receptor (ER) negative breast cancers (orange dots)." (PMID 40562540, 2025). "The present study also showed that gain of DEK and BIRC5 genes, which seems not to be involved in the PI3K or ER pathway, had clear prognostic significance in patients with breast cancer, suggesting presence of other pathways exhibiting crosstalk with the PI3K or ER pathway." (PMID 23679233, 2013).
acute myeloid leukemia (24 papers, 2005 to 2026). Acute myeloid leukemia (AML) is a group of neoplasms arising from precursor cells committed to the myeloid cell-line differentiation. "NUP214 forms a fusion gene with the DEK gene on chromosome 6 in a t translocation associated with acute myeloid leukemia and myelodysplastic syndrome." (PMID 31221207, 2019). "DEK is a proto-oncogene that has been linked to both DNA conformation and splice site selection and is known to be chromosomally translocated in a subset of acute myeloid leukemias." (PMID 33348896, 2020). "DEK overexpression has been seen in many neoplasms, including chronic lymphocytic leukemia and acute myeloid leukemia." (PMID 35769815, 2022). "DEK was originally identified as a fusion protein with the CAN/NUP214 nucleoporin in a patient with acute myeloid leukemia harboring the chromosomal translocation (t6;9)(p23;q34)." (PMID 29538372, 2018). "DEK was originally identified in acute myeloid leukemia as a fusion protein with NUP214, and was subsequently shown to be overexpressed at the mRNA and protein levels in various cancer types including squamous cell carcinoma (SCC)." (PMID 28558019, 2017). "The DEK oncogene, located on 6p22.3, was initially identified in acute myeloid leukemia as a partner of the DEK-CAN fusion gene." (PMID 28558048, 2017). "DEK plays a potential role in hematopoiesis and is dysregulated in acute myeloid leukemia and chronic lymphocytic leukemia; however, the involvement of DEK in T-ALL remains unknown." (PMID 35769815, 2022). "CAN has also been found fused with DEK in a subtype of acute myeloid leukemia, suggesting that CAN is an oncogene activated by fusion with SET or DEK." (PMID 24710090, 2010). "DEK was initially discovered as a fusion protein with a nucleoporin (DEK-CAN, a.k.a.: DEK-NUP214) in a subset of acute myeloid leukemia (AML) patients, and indeed, DEK does play a role in disorders of white blood cell function, including autoimmune disorders and malignancies like AML." (PMID 36275000, 2022). "The oncogene DEK is located on human chromosome 6p22.3 and was originally identified as a fusion to the 3′ portion of the chromosome 9 NUP214 (CAN) gene in a specific subtype of acute myeloid leukemia (AML) patients." (PMID 35563178, 2022).